AGO2 (argonaute RISC catalytic component 2)
Diseases named in the same sentence as AGO2 in open-access papers (continued):
Sharing a sentence is not in itself a finding about the gene and the disease.
tumor (continued). "Therefore, knockout of AGO2 suppressed tumor growth and size in HCC in vivo." (PMID 32420319, 2020). "However, in melanoma cells, downregulation of AGO2 is able to confer cell and tumor-growth." (PMID 32503341, 2020). "MSI1 could promote tumor progression through interaction with Ago2 in glioblastoma." (PMID 32448364, 2020). "We demonstrated in vitro and in vivo that C-terminal terminus of MSI1 could work as a decoy to disrupt the endogenous MSI1/AGO2 interaction, and to efficiently block the oncogenic functions of the endogenous MSI1/AGO2 complex as well as inhibit xenograft tumor growth." (PMID 31903115, 2020). "Furthermore, to investigate whether the increased miR-19b by AGO2 acetylation also influences tumor growth in vivo, each of stable A549 cell lines was subcutaneously inoculated into the backs of nude mice." (PMID 30305728, 2019). "Therefore, Ago2 quantification could be used to improve subtype classification in heterogeneous tumours, or tumours with borderline ER/PR staining." (PMID 31324173, 2019). "Finally, the expression of DICER1 and AGO2 is correlated with tumor subtype and may explain some of the changes in miRNA expression observed." (PMID 17922911, 2007). "For example, by directly attaching to the 3′UTR of FBXO47, tRF-3019a can engage with AGO2 to suppress the expression of FBXO47 and enhance the invasion ability of tumor cells." (PMID 40001986, 2025). "Our analysis revealed a positive correlation between AGO2 expression and adverse clinical outcomes in ACC, including poorer survival, higher Weiss scores, and advanced tumor stages, emphasizing its potential as a biomarker." (PMID 39404265, 2024). "The prognostic potential of AGO2 in ACC was further explored by correlating clinicopathological characteristics with AGO2 mRNA expression in the TCGA-ACC cohort and with the concentration of the AGO2 protein in a cohort from the Kolling Tumour Bank." (PMID 39404265, 2024). "As Ago2/CAV1 interaction promotes mesenchymal and invasive phenotypes of cancer cells in culture, we investigated the role of Ago2/CAV1 interaction in tumor metastasis." (PMID 38649663, 2024). "The increase or potential de-repression of the target mRNAs in 3D tumor spheroids phenocopied the increase observed for cells grown to high density and NLS-AGO2 cells that had been engineered to have AGO2 localized to cell nuclei rather than cytoplasm." (PMID 38109320, 2024). "The significantly suppressed tumor growth and prolonged survival rates in PDX tumor models by decoy peptides evidently provided a new rationale for stratifying patients with MSI1/AGO2-targeted therapeutics." (PMID 35158774, 2022). "Moreover, H1299 tumors that developed in the presence of Ago2 overexpression alone or with TAp63 exhibited much less neovascularization than the control H1299 tumors, while H1299 tumors that developed in the presence of Ago2 and ΔNp63 manifested higher vascular density and larger tumor size." (PMID 35459267, 2022). "We previously reported that MSI1 mediates stress-induced conditions, such as hypoxia and chemotherapeutic treatments, tumor progression, and recurrence of GBM by translocation to the cytosol and interaction with AGO2." (PMID 35158774, 2022). "The expression of CNV-amplified m7G regulators was markedly higher in HCC specimens than in normal control specimens, such as AGO2, NCBP2, GEMIN5 and LARP1, while the expression of EIF4E3 was significantly lower in tumor specimens." (PMID 36389726, 2022). "Through coordinating both ERVs and AGO2 expression, MLL4 ablation results in a dramatic increase of cytosolic dsRNAs and consequently triggers interferon signaling in murine tumor cells." (PMID 36323669, 2022).
tumor (continued). "Analysis of the xenograft tumor samples indicated the effectiveness of Pep#11/Pep#26 peptides on tumor growth, MSI1/AGO2 interaction, and the downstream mRNA targets." (PMID 35158774, 2022). "In this research, we studied the function of AGO2 in CRC tumor specimens and CRC cells and explored the possible molecular mechanism of AGO2 in CRC." (PMID 33846300, 2021). "In this study, we observed a reduction in AGO2 protein, a core component of the RISC complex, in CRC tumor tissues compared to their normal counterparts." (PMID 33846300, 2021). "Another study showed that AGO2 mRNA and protein levels were upregulated in HCC tissues and that AGO2 expression can be regulated by the tumor-suppressive miR-99a." (PMID 31906510, 2020). "The pull-down assay showed that circ-ZFR was enriched in the AGO2 pellet compared with those in the input control, suggesting circ-ZFR also bind to AGO2 to regulate microRNA levels in tumor cells." (PMID 33928018, 2020). "Further, YTHDF2 facilitates YAP mRNA decay via the AGO2 system in normal tissue, while YTHDF1 promoted YAP mRNA translation by interacting with eIF3a in tumor tissue." (PMID 32106857, 2020). "In the present study, we investigated the molecular mechanisms through which LINC01234 regulated the tumor progression-related behavior of NSCLC cells, and found that LINC01234 interacted with several RNA-binding proteins, including Ago2, EZH2, LSD1 and SUZ12." (PMID 31959200, 2020). "After measuring and quantifying the levels of Ago2 in a Tissue Microarray (TMA), the results were correlated with key clinicopathological criteria (including age, stage, subtype, tumour size and survival outcomes)." (PMID 31324173, 2019). "Some studies have already reported a tumor specific expression of AGO1, AGO2, Dicer and Drosha in the urogenital tract." (PMID 29857476, 2018). "We next investigated the efficacy of miR-558 over-expression and knockdown of AGO2, eIF4E, or HIF-2α against tumor growth, metastasis and angiogenesis in vivo." (PMID 27276678, 2016). "Over-expression ofLin-41 can suppress the expression of the Ago1 and Ago2 of RISC and this suppressioncan promote the growth of tumor cells." (PMID 25012758, 2014). "We also observed significant changes in AGO2, DICER1 and DROSHA expression in relation to ER status, with AGO2 and DROSHA being higher and DICER1 lower in ER- tumor samples." (PMID 17922911, 2007). "Ago2/CAV1 interaction plays a role in miRNA-mediated mRNA suppression and in miRNA release via extracellular vesicles (EVs) from tumors into the circulation, which can be used as a biomarker of tumor progression." (PMID 38649663, 2024). "We found that Trp complex isolated from CT26 cells pretreated with BCI‐137 does not inhibit CT26 growth, suggesting that Ago2 is indeed involved in the Trp complex mediated inhibition of CT26 tumor cell growth." (PMID 39031551, 2024). "Bioinformatic analyses reveal that AGO2 expression is negatively correlated with the mRNA levels of CD3, CD8A, and GZMA in a variety of TCGA human tumor types, indicating AGO2-low tumors have a higher abundance of total and CD8+ T cells and stronger immune cytotoxic activity." (PMID 36323669, 2022). "We next tested whether Ago2, under the guidance of p63 isoforms, potentiates H1299 or SCC9 tumor progression in vivo." (PMID 35459267, 2022). "In conclusion, our findings provide evidence to support the tumor-suppressive role of PTEN, whose gain in responding to UA could decrease the CSC portion by downregulating the expression of AGO2." (PMID 36613808, 2022). "It was reported that AGO2, as a component of the RNA-induced silencing complex, was capable of inhibiting protein translation by binding to the m7G cap of EIF4E, which was essential in the translational process of tumor progression." (PMID 36761423, 2022). "Additionally, circAGO2, derived from the Argonaute 2 (AGO2) gene, is part of a miRNA-induced silencing complex involved in tumor progression that binds and activates the ELAVL1 protein." (PMID 36477660, 2022).
tumor (continued). "Similarly, in LUSC, higher expression of AGO2, EIF3D, and LSM1 were positively correlated with tumor stem cell score but negatively correlated with immune infiltration degrees, indicating a poor prognosis." (PMID 36226166, 2022). "We also established xenograft tumors in mice and found that the tumor volume of the AGO2-knockdown group was not significantly different from that of the control group." (PMID 33846300, 2021). "Subsequently, miRNA-targeted mRNAs cannot be loaded to the M1-Ubi modified AGO2/miRISC, thus the overall miRNA-targeted mRNAs are not degraded and stabilized in hypoxic tumor cells." (PMID 34518544, 2021). "As MSI1 engages AGO2 to promote tumor progression through mRNA regulation, we asked whether the disruption of MSI1/AGO2 interaction could affect the tumor growth driven by cytosolic MSI1." (PMID 31903115, 2020). "Investigating the fitting of complete-case saturated and Imputed-dataset saturated models for DFS, the models fitted 177 (of 308) complete-case individuals across the modelled variables [Ago2 staining intensity, Subtype, Nottingham Prognostic Index (NPI), Tumour size, disease stage, patient age]." (PMID 31324173, 2019). "Moreover, AGO2 has been found phosphorylated by AKT at S387 and indirectly inhibits tumor cell proliferation and tumor growth." (PMID 28903378, 2017). "As we found many changes in miRNA expression across the five clinical tumor subtypes we had defined above, we asked whether DICER1, DROSHA, DGCR8, AGO1, AGO2, AGO3 or AGO4 expression differs among these subgroups." (PMID 17922911, 2007). "It is certainly also possible that not all samples of human tumor will have nuclear AGO2 because some tumors or other tissues might escape miRNA regulation by downregulating TNRC6." (PMID 38109320, 2024). "In addition, YTHDF2 could also speed up YAP mRNA degradation through the Argonaute 2 (AGO2) system, inhibiting tumor cell proliferation and metastasis to mitigate disease progression." (PMID 36870954, 2023). "Additionally, AGO2 has been found to interact with the ERβ receptor, a protein exerting tumor suppressive functions, which regulates both canonical and non-canonical AGO2 activities." (PMID 33668654, 2021). "Furthermore, we show that high AGO2 gene expression levels in ERα+ tumors correlate with a poor prognosis, in contrast to a lack of correlation between AGO2 expression levels and clinical outcome for ERα− tumor types." (PMID 29657266, 2016). "However, we unexpectedly found that circSCAP could sponge miR-365b-3p on AGO2 but not exerted tumor-suppressing function through it." (PMID 35365208, 2022). "Based on these results, it is possible to speculate that miR-145-5p behaves as a tumor suppressor miRNA when it is complexed with Ago2 protein, while miR-145-5p activity may become oncogenic in the absence of Ago2, through the interaction with other RNA-binding proteins (RBPs), as for example Ago1." (PMID 30622242, 2019). "Unlike normal cells, tumor-derived exosomes contain various enzymes that are involved in miRNA synthesis and regulation, such as DICER, TRBP (TAR (trans-activation response) RNA-binding protein), and AGO2 (protein argonaute-2)." (PMID 31752198, 2019). "Furthermore, key regulators of the miRNA pathway, including DROSHA, DGCR8, AGO1 and AGO2 are frequently overexpressed—rather than downregulated—in HCC, and specifically AGO2 overexpression has been shown to promote HCC progression, tumor vascularization and metastasis." (PMID 31732746, 2019).
cancer (140 papers, 2009 to 2026). A tumor composed of atypical neoplastic, often pleomorphic cells that invade other tissues. "This aligns with evidence that 3’UTR shortening is a hallmark of the cancer cell transcriptome and that certain oncogenic mutations can impair the AGO2 activity, impacting miRNA regulation." (PMID 39980011, 2025). "The increased plasma membrane association of Ago2 in cancer cells corresponds with the observation that PDAC progression is associated with increased plasma membrane localization of Ago2." (PMID 38649663, 2024). "Blocking Ago2/CAV1 interaction with P2 peptides increased the levels of SCAI mRNAs in A549 cancer cells, which are inversely associated with the levels of miR-3613-3p." (PMID 38649663, 2024). "We observed that the association of Ago2 with the plasma membranes and with endosomes increases in cancer cells, compared to that of normal epithelial cells (Di, Diii, E–G and EV2E)." (PMID 38649663, 2024). "It has been shown that S387 phosphorylation of Ago2 controls Ago2 association with endosomes in cancer cells." (PMID 38649663, 2024). "Among different stages of carcinoma, the levels of plasma membrane-associated Ago2 increased in stage IIIB carcinomas, which are large primary tumors that have spread to nearby lymph nodes (Fig. EV4B)." (PMID 38649663, 2024). "AGO2 bound to Ras and the loss of AGO2 inhibited cancer cell proliferation, senescence, and Ras signaling." (PMID 36834846, 2023). "Overexpression of Ago2 accelerates malignant transformation in some tumors and is associated with low overall survival of some cancer patients." (PMID 35459267, 2022). "In particular, EGFR is known to affect miRNA maturation through the posttranslational modification of Ago2, thus highlighting the important relationship between a cancer mutation and miR-21 status." (PMID 36139366, 2022). "Modifications in Dicer1/Ago2 expression result in huge alterations of miRNA expression, which commonly occur in cancer through either germline deletions, mutations, or promoter methylation." (PMID 34721577, 2021). "The deregulation of AGO2, which is the most abundant member of the family, has been associated with tumorigenesis and cancer progression and, therefore, it has been suggested for therapeutic intervention and treatment." (PMID 32503341, 2020). "Other analyses have shown that 5′ tRFs poorly associate with Argonaute proteins Ago1 and Ago2 in the human cancer line HeLa." (PMID 26703738, 2015). "Recently, alterations (genomic amplifications and/or over-expression) of the AGO2 gene have been extensively described in a variety of cancers, and these alterations have been shown to be linked with an increased metastasis and poorer prognosis." (PMID 26545861, 2015). "All together, these observations indicate that AGO2 is associated with the development of NPC by regulating expression of numerous cancer related genes." (PMID 26545861, 2015). "The polymorphisms in the AGO2 gene have been used to search for susceptibility alleles of a wide spectrum of cancers." (PMID 26545861, 2015). "There are emerging evidence from in vitro analysis and clinical samples that abnormal expression or enzymatic function of AGO2 is associated with cancer development and its progression." (PMID 22639842, 2012). "Having determined that there is substantial translocation of AGO2 into the nucleus in cancer cells when Lamin A levels are diminished and that loss of Lamin A affects gene expression and miRNA profiles, we next aimed to further understand AGO2 function in the nucleus." (PMID 38994560, 2024). "To investigate if GRB2-mediated regulation of AGO2 could affect the cell cancer phenotype we performed migration assays in HEK293T cells which were overexpressing GFP-tagged AGO2 WT or the GRB2-binding-deficient mutant GFP-AGO2 4A." (PMID 37328606, 2023).
cancer (continued). "Our study suggests that an increase in the protein stability, catalytic activity, or nuclear localization of Ago2 may underlie the increased expression of miR-183/96/182 in cancer." (PMID 37810246, 2023). "Furthermore, an increase in Ago2 protein amount along with post-translational modifications of Ago2, such as phosphorylation of tyrosine and serine residues and acetylation of lysine residues, is associated with poor prognosis and survival of cancer patients." (PMID 37810246, 2023). "While further efforts to target this interaction await cocrystalization and structural determination of AGO2 with RAS variants, a greater understanding of the AGO2–RAS interaction in human cancer may inform future clinical targeting of mutant RAS." (PMID 35923912, 2022). "As for miRNAs, also Ago2 deregulation has been linked to cancer progression and treatment." (PMID 30622242, 2019). "Together, our results support the AGO2 gene as a susceptibility gene for cancers." (PMID 26545861, 2015). "Furthermore, the co-localisation of P-gp and Ago2 indicates a close association between the resistance proteins and biogenesis machinery in the MP-mediated acquisition of multidrug resistance in cancer." (PMID 26082317, 2013). "Theoretically, the genetic variants such as single nucleotide polymorphisms (SNPs) within the AGO2 gene, which may alter the expression of AGO2 and then influence the miRNAs processing and function, could result in genotype-dependent differences in risk of cancers." (PMID 26545861, 2015). "The mechanism of how AGO2 SNPs regulates human susceptibility to cancer is unknown." (PMID 26545861, 2015). "Although likely, we can not generalize our results to other viral pathogens and/or other disease models, like cancers, which show increase accumulation of nuclear AGO2." (PMID 40219968, 2025). "AGO2 directly interacts with the oncogene KRAS; elevated AGO2 levels enhance neoplastic transformation in KRAS-driven cancers, whereas AGO2 knockout results in growth arrest." (PMID 41154621, 2025). "Once bound, Ago2 and sncRNA can either activate or repress transcription near promoters, as observed at multiple gene loci in cancer cells and mammalian cardiomyocytes." (PMID 40861070, 2025). "Collectively, genetic and post-translational regulatory mechanisms act as molecular switches that control AGO2’s interaction, activity, and localization, with significant implications for development, cancer, and neuronal function." (PMID 41154621, 2025). "With this interaction in cancer cells, CAV1 sequesters Ago2 on the plasma membranes of cancer cells and regulates the process of selective Ago2/miRNA-mediated translational repression in a compartment-dependent manner." (PMID 38649663, 2024). "AGO2 is a key regulator of miRNA function and maturation, with variable expression across cancer types." (PMID 39404265, 2024). "Only miRNA-3613-3p and miRNA-877-5p were altered with Ago2/CAV1 interaction in both cancer cells and plasma EV of cancer cell-bearing mice (Blue)." (PMID 38649663, 2024). "Many of these Ago2/CAV1-dependent aggressive phenotypes of cancer cells (i.e., invasion, metastasis, EMT, drug resistance, and stemness, are associated with miR-3613-3p-mediated suppression of SCAI." (PMID 38649663, 2024). "Because Ago2/CAV1 interaction regulates the distribution of Ago2 in intracellular compartments of cancer cells in culture, we examined the effects of this interaction on the distribution of Ago2 in tumors in vivo." (PMID 38649663, 2024). "In cancer cells treated with P2 peptides, Ago2 was disassociated from CAV1 on the plasma membranes, but Ago2 was still co-located with CAV1 on the plasma membrane of P2S-treated cancer cells." (PMID 38649663, 2024). "CircAGO2, derived from the AGO2 gene, regulates AGO2-miRNA complexes and cancer progression by interacting with HuR protein and thereby reducing the gene silencing pathways mediated by AGO2/miRNA network." (PMID 40809111, 2024).